NUP153 (nucleoporin 153)
Diseases named in the same sentence as NUP153 in open-access papers (continued):
Sharing a sentence is not in itself a finding about the gene and the disease.
tumor (8 papers, 2010 to 2025). "Immune infiltration analysis, cross-validated using seven independent algorithms, demonstrated a significant association between NUP153 expression and immune cell infiltration levels within the tumour microenvironment." (PMID 40607419, 2025). "To further explore the functional network of NUP153, we used the TCPA database to analyse its association with tumour-related functional proteins." (PMID 40607419, 2025). "The results indicate that NUP153 plays a key role in modulating the immune microenvironment and driving tumour progression, positioning it as a potential target for future therapeutic interventions." (PMID 40607419, 2025). "This lays a foundation for future mechanistic studies and therapeutic exploration targeting NUP153 in tumours with distinct genetic profiles." (PMID 40607419, 2025). "Another NUP factor, NUP153, is specifically required for 53BP1 nuclear import, a mediator of cellular DNA damage response, and a tumor suppressor whose accumulation on damaged chromatin promotes DNA repair and enhances DNA repair response." (PMID 34975746, 2021). "The SENP1 expression level positively correlated with the expression levels of UBN1, SP3, SAP130, NUP98, NUP153 in 32 tumor types." (PMID 34276383, 2021). "In the present study, we found that Nup153 is overexpressed in primary and metastatic PCa tumor cells as compared to benign lesions." (PMID 29963256, 2018). "Co-IP for eNOS confirmed an interaction between Nup153 and eNOS that was stronger in tumor (PCa, C38IM and C27IM) as compared to BPH (C17IM) cells used as normal control." (PMID 29963256, 2018). "We systematically evaluated the regulatory role of NUP153 in the tumour immune microenvironment." (PMID 40607419, 2025). "Understanding these mechanisms could offer new perspectives on how NUP153 contributes to tumour heterogeneity." (PMID 40607419, 2025). "Moreover, the widespread expression pattern of NUP153 provides valuable insights for further exploration of its involvement in tumour initiation and progression." (PMID 40607419, 2025). "Nup153 maintains nuclear envelope architecture and is required for cell migration in tumor cells." (PMID 34386417, 2021). "Notably, after Nup153 depletion (siNup153), a reduction of migration capacity and colony formation in primary tumor-derived and metastatic PCa cells was observed." (PMID 29963256, 2018). "Furthermore, Nup153 is important for tumor cell migration and proliferation which are essential features of metastatic cancers." (PMID 29963256, 2018). "Tumours with high NUP153 expression may exhibit stronger invasiveness." (PMID 40607419, 2025). "The increased expression of nucleoporins Nup153 and Nup214 and importin-beta factors strongly predicts elevated MAPK nuclear import in tumor tissues." (PMID 20174585, 2010). "Therefore, combining our findings, targeting NUP153 could become a potential strategy to inhibit NET formation and tumour metastasis." (PMID 40607419, 2025). "A significant reduction of migration capacity as well proliferation was found in primary tumor-derived (C27IM, not shown) and metastatic (LNCaP) PCa cells undergoing to Nup153 downregulation as shown by scratch test and colony formation assay." (PMID 29963256, 2018). "Moreover, under estrogen induction, these effectors bind to Nup153 promoter region, increasing its protein level and consequently the nuclear import of eNOS/ERβ thus amplifying the effects on gene expression alteration and contributing to tumor aggressiveness and the negative prognosis for PCa." (PMID 29963256, 2018).
heart (1 paper, 2012). "This study shows alterations in specific proteins (NDC1, Nup160, Nup153 and Nup93) that compose NPC in ischaemic and dilated human heart." (PMID 23152829, 2012).
NUP153 also shares sentences with these, for which no sentence is quoted: colorectal adenocarcinoma (2 papers); atrial fibrillation (1); brain tumors (1); breast (1); cholangiocarcinoma (1); colon adenocarcinoma (1); congenital heart disease (1); dilated cardiomyopathy (1); Duchenne muscular dystrophy (1); glioma (1); head and neck squamous cell carcinoma (1); kidney cancer (1); lung adenocarcinoma (1); lung squamous cell carcinoma (1); metastatic prostate carcinoma (1); oesophageal cancer (1); pancreatic ductal adenocarcinoma (1); pheochromocytoma and (1); pneumonia (1); prostate tumors (1); Sepsis (1); uveal melanoma (1).